TMEM175 (transmembrane protein 175)
Description:
Proton-activated proton channel that catalyzes proton efflux from endosomes and lysosomes to maintain a steady-state pH. Activated at low pH (under pH 4.6) by luminal side protons: selectively mediates lysosomal proton release from lysosomes, eliciting a proton leak that balances V-ATPase activity to maintain pH homeostasis. Regulation of lumenal pH stability is required for autophagosome-lysosome fusion. Also acts as a potassium channel at higher pH, regulating potassium conductance in endosomes and lysosomes. Constitutes the pore-forming subunit of the lysoK(GF) complex, a complex activated by extracellular growth factors. The lysoK(GF) complex is composed of TMEM175 and AKT (AKT1, AKT2 or AKT3), a major target of growth factor receptors: in the complex, TMEM175 channel is opened by conformational changes by AKT, leading to its activation. The lysoK(GF) complex is required to protect neurons against stress-induced damage.
Synonyms: hTMEM175; MGC4618
Tractability: Small molecule: a structure with a bound ligand is known. Antibody: UniProt places it where antibodies can reach, with high confidence; UniProt predicts a signal peptide or a membrane-spanning region. PROTAC: its protein half-life has been measured.
Gene: Protein-coding gene on chromosome 4 (932,168 to 958,741, forward strand). Ensembl gene ENSG00000127419.
Subcellular location: Endosome membrane; Lysosome membrane
Subcellular location (Human Protein Atlas): Nuclear membrane; Nucleoplasm
Gene Ontology:
Molecular function: arachidonate binding; potassium channel activity; potassium ion leak channel activity; protein binding; proton channel activity
Biological process: lysosomal lumen pH elevation; potassium ion transmembrane transport; proton transmembrane transport; neuron cellular homeostasis; phagosome-lysosome fusion
Cellular component: endosome; endosome membrane; lysosomal membrane; lysosome
Genetic constraint (gnomAD): Loss-of-function variants: 37 observed, 37.58 expected, observed/expected ratio (o/e) 0.98, 90% interval 0.76 to 1.29. The upper end of that interval is the gene's LOEUF score, 1.29, which puts it in group 5 of 6, group 1 being the genes least tolerant of losing a copy. Missense variants: 704 observed, 679.31 expected, observed/expected ratio (o/e) 1.04, 90% interval 0.97 to 1.1. Synonymous variants: 339 observed, 306.68 expected, observed/expected ratio (o/e) 1.11, 90% interval 1.01 to 1.21.
Homologues: Orthologues: chimpanzee TMEM175 (99% identical), macaque TMEM175 (96% identical), rat Tmem175 (81% identical), mouse Tmem175 (81% identical), dog TMEM175 (81% identical), pig TMEM175 (81% identical), guinea pig TMEM175 (80% identical), zebrafish tmem175 (58% identical).